BRCA2 (BRCA2 DNA repair associated)
Diseases named in the same sentence as BRCA2 in open-access papers (continued):
Sharing a sentence is not in itself a finding about the gene and the disease.
breast cancer (continued). "The estimated cumulative risk of developing breast cancer by the age of 70 in BRCA1 and BRCA2 mutation carriers varies between 43% to 88%; similarly, between 11% to 59% of mutation carriers will develop ovarian cancer by the age of 70." (PMID 24698998, 2014). "b) modified transmission of BRCA2 gene leads to the appearance of breast cancer and especially to the appearance of ovarian cancer." (PMID 25408768, 2014). "The principal genes involved in the risk of breast cancer are BRCA1 and BRCA2, which account for about 20-50% of all HBC cases." (PMID 24986639, 2014). "Tumor gene expression studies of BRCA-mutations in malignant canine mammary tumors have shown varied results with under-expression of BRCA1 in malignant, as well as over-expression of BRCA2 in metastatic tumors." (PMID 24641873, 2014). "Familial breast cancer patients and at risk individuals were previously investigated for BRCA1 and BRCA2 mutations and some were positive for BRCA1/2 mutations." (PMID 24906410, 2014). "A number of these histopathological features have been incorporated into prediction models or have been proposed as selection criteria for prioritizing testing of breast cancer patients for BRCA1 and BRCA2 mutations." (PMID 25857409, 2014). "Although this article has focused on the utility of histopathologic features of breast cancers in the context of the classification of variants in the BRCA1 and BRCA2 genes, these results should also be useful in a range of other applications." (PMID 25857409, 2014). "The potential link between breast cancer and childhood cancer is of great interest, given past reports of increased rates of childhood cancer in families carrying a BRCA1 or BRCA2 mutation." (PMID 24799902, 2014). "The estimated lifetime risk of developing breast cancer for women with BRCA1 and BRCA2 mutations is 40% to 85%." (PMID 25184114, 2014). "In canine mammary carcinomas, BRCA2 and RAD51 show similar regulations, which indicates similar functions." (PMID 24641873, 2014). "From the original publication of the two most widely known breast cancer (BC) susceptibility genes, namely BRCA1 and BRCA2, there has been an active pursuit of new genes contributing to the familial BC phenotype." (PMID 23409019, 2013). "Decreased expression of BRCA2 has been suggested to be a marker for a favorable response to docetaxel in breast cancer." (PMID 24289229, 2013). "The identification of the two most prevalent susceptibility genes in breast cancer, BRCA1 and BRCA2, was the beginning of a sustained effort to uncover new genes explaining the missing heritability in this disease." (PMID 23409019, 2013). "Biallelic mutations of some of these hereditary breast cancer susceptibility genes, namely BRCA2/FANCD1, BRIP1/FANCJ, PALB2/FANCN and RAD51C/FANCO, have been identified in patients with Fanconi anemia (FA, [MIM 227650])." (PMID 23840564, 2013). "For example, linkage analysis of non-BRCA1 breast cancer families with a case of male breast cancer, led to the discovery of the BRCA2 locus." (PMID 23383274, 2013). "This strongly suggests that this VUS is of high clinical significance and impact breast cancer by negatively affecting the interaction between BRCA2 and RAD51." (PMID 23704879, 2013). "Approximately 7% of all breast cancers present a familial breast cancer history, and around 25% of these have germline mutations in BRCA1 and BRCA2 genes." (PMID 23326384, 2013).
breast cancer (continued). "About 10% of breast cancer is attributable to genetic predisposition, with approximately 30% familial cases due to BRCA-1 or BRCA-2 genes mutations." (PMID 23282240, 2013). "Germline mutations in the human breast cancer genes BRCA1 and BRCA2 account for a substantial proportion of familial, early-onset breast and ovarian cancers." (PMID 24137399, 2013). "The results of this prospective cohort study will provide valuable information regarding the risk reducing potential of modifiable risk factors for breast cancer in unaffected BRCA1 and BRCA2 gene carriers." (PMID 23517070, 2013). "- PALB2: Subsequently, the “partner and localiser of BRCA2”, PALB2, has been identified as another breast cancer susceptibility gene." (PMID 24025454, 2013). "- BRCA1 and BRCA2: The prototypic BRCA1 and BRCA2 mutations confer a very high life-time risk for breast cancer in the range of 55-85% for BRCA1 and 35-60% for BRCA2, compared with an about 10% population risk." (PMID 24025454, 2013). "Our finding agrees with previous observations in cervical cancers with high DSS1 expression and in breast cancers with high BRCA2 expression." (PMID 24289229, 2013). "Because DSS1, a mammalian component of the transcription/RNA export complex, is known to stabilize BRCA2, we investigated how the expression of DSS1 is associated with clinical parameters in breast cancers." (PMID 24289229, 2013). "A meta-analysis of 22 studies by Antoniou and colleagues found the cumulative risk of breast cancer by age 70 to be 65% in BRCA1 and 45% in BRCA2 mutation carriers." (PMID 23941127, 2013). "In the present study, we have performed microarray gene expression profiling for molecular characterization and classification of BRCA1, BRCA2, and sporadic (unselected) breast cancers." (PMID 23704984, 2013). "Type II carcinomas also often feature alterations of the tumor suppressor genes breast cancer 1, early onset (BRCA1) and breast cancer 2, early onset (BRCA2) and are in general genetically unstable." (PMID 23644885, 2013). "High-penetrance breast cancer susceptibility genes, such as BRCA1 and BRCA2, have low mutation rates and therefore explain only a small fraction of breast cancers in the general population." (PMID 23565189, 2013). "Women bearing an alteration in BRCA1 or BRCA2 develop during their lifespan a breast cancer in 50–80 % of cases and an ovarian cancer in 20–40 % of cases (carriers of BRCA1 mutation) or in 10–20 % of cases (carriers of BRCA2 mutation)." (PMID 23354980, 2013). "QBS allows physicians to bedside recognize in quantitative way and precisely localize from birth both breast cancer IRR and the presence of BRCA-1 as well as BRCA-2 mutations." (PMID 23533376, 2013). "BRCA1 (MIM 113705) and BRCA2 (MIM 600185) genes are responsible for approximately 20-40% of inherited breast cancer." (PMID 23683081, 2013). "Most currently known breast cancer predisposition genes play a role in the repair of DNA double-strand breaks by homologous recombination: BRCA1 and BRCA2, associated with a high risk of breast cancer, and BRIP1 and PALB2, associated with a moderate risk." (PMID 24139550, 2013). "The Breast Cancer Linkage Consortium Genetic heterogeneity and penetrance analysis of the BRCA1 and BRCA2 genes in breast cancer families." (PMID 24711870, 2013). "Some of the key genetic mutations associated with breast cancer, such as BRCA1 and BRCA2 (human genes that belong to a class of genes known as tumor suppressors), have also been found in some individuals with prostate cancer." (PMID 24351742, 2013).
breast cancer (continued). "Characteristics of observational studies of the relation between polymorphic repeat length in the AIB1 gene and breast cancer risk in BRCA1 and BRCA2 mutation carriers included in the meta-analysis." (PMID 23483928, 2013). "In a population-based study, mutations in the two predominant breast cancer susceptibility genes, BRCA1 and BRCA2, accounted for approximately 20% of familial breast cancer diagnoses." (PMID 24137204, 2013). "We carried out a meta-analysis focusing on the relationship between length of AIB1 gene poly-Q repeat domain as a modifier of breast cancer (BC) susceptibility in patients with BRCA1 and BRCA2 mutation carriers." (PMID 23483928, 2013). "However, further analysis of a significant number of BRCA1 and BRCA2 missense variants of uncertain significance (VUS) continue to pose an important obstacle to the clinical management of a considerable portion of familial breast cancer probands and families who carry such VUS." (PMID 23704879, 2013). "Mechanism of developing breast cancer is still unclear but the contribution of mutation in BRCA1 and BRCA2 have been reported to be associated with a dominantly increased risk of disease." (PMID 23659667, 2013). "Given that BRCA2 mutations are more frequent in male breast cancer, FGFR2 levels were expected to be higher in male than in female breast cancer." (PMID 23308200, 2013). "Especially in patients that carry germ line mutations in tumor suppressor genes such as BRCA1 or BRCA2, acquired LOH of the wild-type allele, corresponding to recessive loss-of-function mutations, will lead to hereditary breast cancer." (PMID 24004841, 2013). "Although numerous RNA profiling studies of breast cancers have been published, only a limited number of studies of breast tumors from BRCA1 and BRCA2 mutation carriers exist." (PMID 23704984, 2013). "On the other hand, differences in the associations of the modifying polymorphisms with breast cancer risk for BRCA1 and BRCA2 mutation carriers are likely to reflect differences in the biology of tumor development in these two groups of women at high risk of BC." (PMID 23483928, 2013). "Studies in humans have shown that breast cancer with BRCA1 mutations and less commonly BRCA2 mutations display predominantly a triple negative immunophenotype with distinct basal-like subtype." (PMID 24004841, 2013). "As compared with BRCA2-associated breast cancer, BRCA1-associated breast cancer had a higher ER-negative rate and larger tumor diameter." (PMID 23318652, 2013). "5%–10% of breast cancer cases are hereditary and are caused by pathogenic mutations in the considered reference BRCA1 and BRCA2 genes." (PMID 23586058, 2013). "Mutations in these genes are rare and early reports suggested that, on average, they are associated with moderate risks of breast cancer (lower than the high breast cancer risks associated with BRCA1 and BRCA2 mutations)." (PMID 23448497, 2013). "Hereditary breast cancer is usually detected in women with family history of breast cancer that was observed among first-degree relatives (mother, sister, and daughter) and is caused by mutations in tumor suppressor genes BRCA1 and BRCA2 in germinal cells." (PMID 24325835, 2013). "Rao et al47 applied the BRCApro, Penn, and Myriad models to 212 Chinese familial breast cancer patients, among whom 33 had BRCA1 or BRCA2 mutations." (PMID 23318652, 2013). "Chen et al40 detected an upstream promoter sequence of −397–+123 bp in BRCA2 in 357 Chinese Han patients with familial or early-onset breast cancer." (PMID 23318652, 2013). "Like BRCA2, PALB2 itself is also mutated in breast cancer, pancreatic cancer, ovarian cancer and Fanconi anemia (FA)." (PMID 23585894, 2013).
breast cancer (continued). "BRCA1 (OMIM 113705) and BRCA2 (OMIM 600185), the two most important breast cancer susceptibility genes, are key players in DDR." (PMID 24159334, 2013). "The identification of breast cancer susceptibility genes, particularly BRCA1 and BRCA2, has revolutionized the management of women with a family history of the disease." (PMID 23941127, 2013). "In some instances, variants have been observed to differentially associate with breast cancer risk in BRCA1 or BRCA2 carriers, and one variant has been reported to specifically associate with BRCA2 mutations." (PMID 24025454, 2013). "The average age for the onset of breast cancer in PALB2 c.1592delT carriers is 53.1 years, which is somewhat higher than in Finnish BRCA1/BRCA2 mutation carriers (45.2/47.4 years), but considerably lower than in sporadic patients (58.0 years)." (PMID 23941127, 2013). "In summary, we have identified a novel locus at 1q32 associated with breast cancer risk for BRCA1 mutation carriers, which was also associated with ER-negative breast cancer for BRCA2 carriers and in the general population." (PMID 23544013, 2013). "Items used in quality scoring for studies of the association between polymorphic repeat length in the AIB1 gene and breast cancer risk in BRCA1 and BRCA2 mutation carriers." (PMID 23483928, 2013). "These relationships are well demonstrated by the observation that the gene products of the early onset breast cancer genes BRCA1 and BRCA2, whose germline loss or mutation confers a near 80% risk of developing breast cancer, are themselves DNA repair proteins." (PMID 23762064, 2013). "Whole genome sequencing in breast cancer identified a characteristic distribution of single nucleotide mutations with an increased overall mutation burden in both BRCA1- and BRCA2-associated tumors." (PMID 24265793, 2013). "In summary our intriguing and novel results point to the potential broader utility of PARP inhibitors in breast cancer beyond hereditary BRCA1-and BRCA2-deficient tumors by combining it with EGFR inhibitors such as lapatinib." (PMID 23071597, 2012). "The sample series includes four cases each of estrogen-receptor (ER)-positive, HER2-positive, and BRCA2-positive breast cancer; three cases of triple negative; and five cases of BRCA1-positive breast cancer." (PMID 22608083, 2012). "Germline mutations in either one of the two major breast cancer tumour suppressor genes, BRCA1 or BRCA2, confer a 60-85% lifetime risk of breast cancer but explain only around 20% of the breast cancer cases that have a family history of the disease." (PMID 22703186, 2012). "In the 1990s, the two major breast cancer susceptibility genes BRCA1 and BRCA2 were identified revealing that harmful mutations in these genes confer to a cumulative disease risk by age 70 years of 65 and 45%, respectively." (PMID 23226154, 2012). "In 2002, the discovery that BRCA2 and FANCD1 are the same gene, provided the first evidence of common genetic bases for breast cancer susceptibility and FA." (PMID 22383991, 2012). "Methionine at amino acid position 1,915 of BRCA2 (rs4987117) was less frequent (OR 0.39, 95% CI 0.19 – 0.82, p = 0.013) in estrogen receptor-positive patients of a study cohort of 117 sporadic breast cancer cases from Poland." (PMID 22666503, 2012).
breast cancer (continued). "During replication, unrepaired SSB will convert into DSB, and in cells deficient in DSB repair via homologous recombination, e.g., breast cancer cells carrying mutations in BRCA1 and BRCA2, cell death will occur." (PMID 23050241, 2012). "It is estimated that 5% to 10% of all breast cancers are attributable to inherited mutations, of which the two most important and highly penetrant are BRCA1 and BRCA2." (PMID 22537934, 2012). "Most cases of hereditary breast cancer are attributable to germline mutations in one of two major breast cancer-predisposing genes, BRCA1 or BRCA2 (BRCA1/2)." (PMID 22257650, 2012). "About 40–50 % of familial breast cancer can currently be explained by mutations in BRCA1 and BRCA2 genes." (PMID 22544570, 2012). "Cancers were typed for estrogen receptors (ER), progesterone receptors (PR), and HER2, and included nine cases with germline mutations in the breast cancer predisposition genes BRCA1 (five) and BRCA2 (four) (available online)." (PMID 22608084, 2012). "Germline mutations in BRCA1 and BRCA2 were analyzed by Sanger sequencing and multiple ligation-dependent probe amplification (MLPA) analysis in 431 women from the Malaysian Breast Cancer Genetic Study, including 110 women with TNBC." (PMID 23116406, 2012). "A few BRCA2 deletions have been previously reported in families with male breast cancer, and contribute to inactivate this gene in breast cancer families." (PMID 22691290, 2012). "Familial linkage studies have identified high penetrance, low frequency mutations in genes such as the breast cancer susceptibility genes BRCA1 and BRCA2 but these mutations only account for approximately 20% of the familial risk." (PMID 23270421, 2012). "Particularly, ESR1, BRCA1 and BRCA2 were less often methylated compared with female breast cancer and were strong independent predictors of gender in logistic regression analysis (P = 0.005, P = 0.010 and P < 0.001, respectively)." (PMID 22765268, 2012). "We and others have evaluated the impact of reproductive factors in the etiology of BRCA-associated breast cancer, although the results are conflicting and vary by BRCA1 or BRCA2 mutation." (PMID 22405187, 2012). "Ethnic variations in breast cancer epidemiology and genetics have necessitated investigation of the spectra of BRCA1 and BRCA2 mutations in different populations." (PMID 22970155, 2012). "We identified 11 BRCA1 (11%) and 6 BRCA2 (6%) germline carriers among early-onset breast cancer patients." (PMID 22507745, 2012). "Some of the genes causing the Fanconi anemia (FA) syndrome, such as BRCA2, BRIP1, PALB2, and RAD51C, are associated with high or moderate risk of developing breast cancer." (PMID 22383991, 2012). "Previous candidate-gene DNA sequencing studies have implicated homologous recombination in breast cancer susceptibility, and BRCA1 and BRCA2 themselves are players in this pathway." (PMID 23028381, 2012). "In contrast to female breast cancer (FBC) there was greater representation of BRCA2 tumours (41.7% vs 8.3%, p=0.0008) and underrepresentation of BRCA1 tumours (5.0% vs 14.4%, p=0.0001)." (PMID 23146383, 2012). "We have investigated eight novel breast cancer susceptibility loci identified through breast cancer GWAS for their associations with breast cancer risk for BRCA1 and BRCA2 mutation carriers using data from the CIMBA." (PMID 22348646, 2012). "The minor rs3803662 allele also increased the risk of breast cancer in BRCA1 and BRCA2 carriers as well as in a population-based study of men." (PMID 23270421, 2012).